USP17L28 (ubiquitin specific peptidase 17 like family member 28)
Description:
Deubiquitinating enzyme that removes conjugated ubiquitin from specific proteins to regulate different cellular processes that may include cell proliferation, progression through the cell cycle, apoptosis, cell migration, and the cellular response to viral infection.
Target class: Enzyme; Hydrolase
Gene: Protein-coding gene on chromosome 4 (9,348,893 to 9,350,485, forward strand). Ensembl gene ENSG00000231051.
Subcellular location: Nucleus, nucleolus; Endoplasmic reticulum
Pathways (Reactome):
Metabolism of proteins: Ub-specific processing proteases
Gene Ontology:
Molecular function: cysteine-type deubiquitinase activity; hyaluronic acid binding; RNA binding
Biological process: positive regulation of epithelial cell apoptotic process; protein deubiquitination involved in ubiquitin-dependent protein catabolic process; regulation of apoptotic process; protein deubiquitination
Cellular component: nucleolus; nucleus; endoplasmic reticulum
Homologues: Paralogues in human: USP17L24 (100% identical), USP17L25 (100% identical), USP17L26 (100% identical), USP17L27 (100% identical), USP17L29 (100% identical), USP17L30 (100% identical), USP17L5 (99% identical), USP17L20 (99% identical), USP17L11 (99% identical), USP17L17 (99% identical), USP17L18 (99% identical), USP17L22 (99% identical), and 59 more.